BDNF (brain derived neurotrophic factor)
Diseases named in the same sentence as BDNF in open-access papers (continued):
Sharing a sentence is not in itself a finding about the gene and the disease.
schizophrenia (continued). "Thus, BDNF likely influences certain cognitive functions, such as decision making or MF, in chronic schizophrenia patients." (PMID 29896133, 2018). "All these data suggest that the altered BDNF function may be involved in schizophrenia pathophysiology." (PMID 30233327, 2018). "The scientific evaluation of exercise induced changes in brain-derived neurotrophic factor (BDNF) concentration is emerging as a key research area in healthy adult populations and in neurodegenerative populations (e.g., multiple sclerosis) (schizophrenia)." (PMID 29568518, 2018). "Accumulating evidence indicates that the expression level of BDNF is altered in schizophrenia." (PMID 30233327, 2018). "Blood BDNF concentrations reflect brain BDNF levels in rats, mice, or pigs, so peripheral BDNF levels might partially reflect a synthesis, secretion and metabolism of brain BDNF in schizophrenia patients." (PMID 29896133, 2018). "Findings from clinical and animal studies of schizophrenia showed that estrogen may provide a protective effect in schizophrenia, including through mediating BDNF expression and activity." (PMID 29867348, 2018). "In addition, it has been reported that the epigenetic regulation of BDNF plays an important role in schizophrenia." (PMID 30233327, 2018). "However, most studies find decreased BDNF levels in the blood of people with schizophrenia and suggest some degree of insulin resistance in clozapine-treated patients." (PMID 29163244, 2017). "In addition, mRNA levels of BDNF and TrkB have been found to be reduced in the prefrontal cortex and hippocampus of patients with schizophrenia." (PMID 35098038, 2017). "Many studies reported that blood BDNF levels of patients with schizophrenia varied." (PMID 29287075, 2017). "The role of BDNF in cognition has also been shown for some animal and human schizophrenia." (PMID 28272307, 2017). "Moreover, decreased mRNA expression of BDNF was detected in the hippocampus of patients with mood disorders and schizophrenia." (PMID 28466254, 2017). "With regard to clinical translation it has been demonstrated that the increase in BDNF serum levels in olanzapine-treated schizophrenia patients may directly correlate with the progressive reduction in positive symptoms." (PMID 29321734, 2017). "Another study, which drew attention to the existence of three different isoforms of BDNF in the serum, (i.e., precursor, mature and truncated forms of BDNF), suggested that individuals with schizophrenia have lower levels of truncated isoform, compared to other forms of BDNF." (PMID 28358316, 2017). "Indeed, both BDNF and neuronal cell death have been found to be involved in the pathophysiology of schizophrenia." (PMID 28924203, 2017). "In addition, schizophrenia patients showed lower basal serum levels of BDNF as compared to healthy subjects." (PMID 29321734, 2017). "However, a study by Durany and colleagues further pointed out an increased BDNF concentration in cortex of individuals with schizophrenia." (PMID 28358316, 2017). "Furthermore, a recent RCT of 20-week resistance training for schizophrenia found significant increases in BDNF." (PMID 27521348, 2017). "This hypothesis is supported by the finding that the decrease in brain-derived neurotrophic factor (BDNF) which occurs in older age is amplified in schizophrenia." (PMID 29201010, 2017). "There seems to be a consensus about the peripheral BDNF levels being decreased in schizophrenia." (PMID 35098038, 2017). "However, the results from the other study suggested a difference in the promotor IV methylation frequency and BDNF gene expression between patients diagnosed with schizophrenia and control subjects." (PMID 28358316, 2017). "Interestingly, after catatonia was relieved by lorazepam, serum BDNF level decreased in patients with schizophrenia." (PMID 28114315, 2017).
schizophrenia (continued). "A growing number of studies implicate BDNF in the pathogenesis of schizophrenia, and consider it an important element in the protection of neurons and in the prevention of the neurobiological changes that may lead to suicide in this disorder." (PMID 35098038, 2017). "The neurotrophin BDNF is an interesting candidate in the search for biomarkers that could improve diagnosis and therapy monitoring in patients with schizophrenia." (PMID 28358316, 2017). "As a whole, the findings indicate the possibility that NPIs may have a favorable effect on blood BDNF in schizophrenia patients, although the efficacy of each NPI was unclear." (PMID 27783051, 2016). "Hence, further research is needed to clarify the effects of NPIs on blood BDNF in healthy subjects, as well as in the patients with psychotic diseases, including schizophrenia." (PMID 27783051, 2016). "Meanwhile, findings from previous studies have noted that a decreased expression of BDNF may be related to schizophrenia patients." (PMID 27783051, 2016). "Despite insufficient evidence to draw a conclusion, our results suggest that use of NPIs as adjunctive treatments, specifically non-exercise interventions, may affect positively serum or plasma BDNF in patients with schizophrenia." (PMID 27783051, 2016). "Taking these findings into account, we hypothesized that a reduced noradrenergic system and BDNF exist in schizophrenia patients." (PMID 26770258, 2016). "BDNF has been widely investigated for its relevance to schizophrenia." (PMID 27895608, 2016). "Firstly, the number of RCTs addressing NPIs on peripheral BDNF in schizophrenia is limited." (PMID 27783051, 2016). "The authors concluded that the poor performance of patients with schizophrenia on the Iowa Gambling Task may be related to impaired sensitivity to reward and punishment due to depressive symptoms and reduced serum BDNF levels." (PMID 27147997, 2016). "Thus, the aim of the current study was to review the efficacy of NPIs on peripheral serum and plasma BDNF in subjects with schizophrenia." (PMID 27783051, 2016). "Future research protocols concerning NPI implementation with a focus on alterations in blood BDNF levels in schizophrenia may find it beneficial to include a follow-up period; Fifthly, a high level of heterogeneity was found among NPIs." (PMID 27783051, 2016). "Collectively, our results suggest that hippocampal astrocytes may contribute to the pathophysiology of schizophrenia symptoms associated with NMDA receptor hypofunction by reactive transformation and altered BDNF signaling." (PMID 26700309, 2015). "A recent meta-analysissupports an overall reduction in peripheral BDNF levels in schizophrenia." (PMID 25162472, 2015). "Our findings suggest that hippocampal astrocytes may participate in the pathogenesis of schizophrenia symptoms associated with NMDA receptor hypofunction, specifically by reactive transformation and altered BDNF signaling." (PMID 26700309, 2015). "Among patients with schizophrenia, a mental illness that is most likely to be accompanied by a decline in cognitive functions, an association was found between BDNF and verbal working memory and negative symptoms." (PMID 26405456, 2015). "Antipsychotics may also contribute to the abnormal relationship between plasma BDNF levelsand caudate activity in schizophrenia." (PMID 25162472, 2015). "The difference between our findings and the majority of other studies on peripheral BDNF inchronically ill people with schizophrenia may be explained by the fact that our patientsample contained some recent-onset patients." (PMID 25162472, 2015). "However, the extent to which alterations inblood BDNF levels relate to abnormal learning-related brain activity in schizophrenia, ascompared to healthy individuals, remains to be demonstrated." (PMID 25162472, 2015).
schizophrenia (continued). "Therefore, in the current study, we evaluated GFAP, BDNF, TrkB, and p75 expression levels in hippocampal astrocytes in the animal model of schizophrenia based on the repeated treatment with MK-801 and/or in primary cultures of hippocampal astrocytes." (PMID 26700309, 2015). "In supportof this possibility, we have found that the normal function of BDNF may be interrupted dueto increased truncated trkB receptors in brains of people with schizophrenia (Wonget al.2013)." (PMID 25162472, 2015). "Mirtazapine may also boost the levels of the Brain-Derived Neurotrophic Factor, a major mediator of neurogenesis and neuroplasticity, which are often abnormal in patients with schizophrenia." (PMID 25991654, 2015). "Taking these findings into account, diminished serum BDNF level in schizophrenia patients may reflect their poor decision-making performance." (PMID 25538582, 2014). "However, the reviewers were unable to account for the heterogeneity across studies, though gender and body mass are known to affect BDNF levels, as are stage of illness, subtype of schizophrenia and medication, substance misuse and diet." (PMID 24672724, 2014). "Candidate gene studies have identified a number of genes, such as catechol-O-methyltransferase (COMT), brain-derived neurotrophic factor (BDNF), neuregulin-1 (NRG-1), and disrupted in schizophrenia (DISC-1) that appear to be shared risk factors for schizophrenia, bipolar disorder, and MDD." (PMID 25202283, 2014). "BDNF alterations in medicated patients with schizophrenia may also reflect the effects of antipsychotic treatment and possible differential impact of first generation antipsychotics (FGAs) relative to second generation antipsychotics (SGAs)." (PMID 24551075, 2014). "The V66M mutation in BDNF impairs activity-dependent release of BDNF in hippocampal cultures and is associated with impaired episodic memory, both in patients with schizophrenia and people without neurologic or psychiatric illness." (PMID 24672476, 2014). "In schizophrenia, decreased expression of TrkB in the prefrontal cortex may contribute to reduced BDNF-TrkB signaling and lead to reduced neuronal plasticity." (PMID 25027171, 2014). "With this background, in the present study, we investigated 53 polymorphisms from five genes (RGS4, SLC6A3, PIP4K2A, BDNF and PI4KA) in 423 south Indian schizophrenia cases segregated into low and high severity of illness to assess their influence on antipsychotic response." (PMID 25025909, 2014). "In addition to antipsychotic treatment, other factors such as stage of illness, gender and genetic makeup seem to play a role in BDNF levels of patients with schizophrenia." (PMID 24551075, 2014). "Since both BDNF and NRG1 are implicated in the pathophysiology of schizophrenia, we examined whether the interaction between TrkB and ErbB4 is altered in schizophrenia." (PMID 25052836, 2014). "Evidence for disturbed BDNF functioning in schizophrenia comes from several different sources." (PMID 24672724, 2014). "The role of antipsychotic medications in the volume alterations of brain structures, and hippocampus in particular, in schizophrenia and the contribution of BDNF in this process remain unclear." (PMID 24551075, 2014). "The type of atypical antipsychotic may also have differential effects on BDNF levels, as it has been shown that patients with schizophrenia on clozapine had higher BDNF levels compared to patients on risperidone." (PMID 24551075, 2014). "Although serum BDNF change might be correlated with weight-reduction magnitude in subjects being treated for schizophrenia, the relationship between BDNF and body-weight might be different due to the influence of gender and antipsychotic treatment." (PMID 24524285, 2014). "They concluded that low BDNF levels at the onset of psychosis suggest that it may contribute to the pathogenesis of schizophrenia and perhaps, could be a candidate biological marker for positive symptoms." (PMID 23785335, 2013).
schizophrenia (continued). "Considering the neurodevelopmental hypothesis about schizophrenia, BDNF has been proposed as a candidate to explain part of the pathogenesis of this disease." (PMID 23785335, 2013). "Thus, the possible role of other genes in the BDNF/NTRK2 signaling pathway and their interactions on susceptibility to schizophrenia should be further examined." (PMID 24069289, 2013). "Impaired signaling, induced by BDNF, has been reported for schizophrenia." (PMID 24300402, 2013). "However, we found the association between the interaction of BDNF and NTRK2 with paranoid schizophrenia by using the MDR method followed by conventional statistical analysis." (PMID 24069289, 2013). "The aim of the current study was to examine the long-term effects of chronic METH treatment in BDNF HETs during young-adulthood on a behavioral endophenotype related to the positive symptoms of schizophrenia, prepulse inhibition (PPI) of the acoustic startle reflex." (PMID 23781174, 2013). "Until now, no literature reported the relationship between BDNF polymorphism rs6265 and paranoid schizophrenia in a Chinese Han population." (PMID 24069289, 2013). "Importantly, Nrg1 can interact with BDNF in regulating neuronal processes, BDNF down-regulation has been reported in schizophrenia, and BDNF expression changes impact on the sensitivity to social defeat stress." (PMID 23966917, 2013). "Neurotrophic tyrosine kinase receptor 2 (NTRK2) is the high-affinity receptor of BDNF, and was reported to be associated with mood disorders, though no literature reported the association with schizophrenia." (PMID 24069289, 2013). "Mounting evidence has demonstrated that BDNF were involved in the pathophysiology of schizophrenia." (PMID 24069289, 2013). "Though an earlier meta-analytic evaluation of these study findings supported decreased peripheral levels of BDNF in schizophrenia patients, further studies on antipsychotic-naïve patients have been recommended by a recent review to avoid the potential confounding effects of antipsychotic treatment." (PMID 23847552, 2013). "Peripheral level of BDNF in schizophrenia patients has been evaluated in many studies." (PMID 23847552, 2013). "Interestingly patients with schizophrenia showed an increase in serum BDNF levels after performing intensive neuroplasticity-based cognitive training." (PMID 23700463, 2013). "Furthermore, increasing postmortem studies have shown that BDNF levels were significantly lower in prefrontal cortex of schizophrenia patients." (PMID 24069289, 2013). "This raises the hypothesis of a link between cortical area, via BDNF, and the dopamine neurotransmission pathway in schizophrenia and its treatment." (PMID 23785335, 2013). "Actually, BDNF has a proven role in neuronal survival and plasticity of dopaminergic neurons, cholinergic and serotonergic neurons, and all of these are pathways involved in the pathophysiology of schizophrenia." (PMID 23785335, 2013). "Given that BDNF levels are reduced in schizophrenia, BDNF HETs may be more likely to show a disturbance of PPI following METH exposure." (PMID 23781174, 2013). "BDNF, FGF2, and DA are known to be key molecules for the causes and biomarker of schizophrenia." (PMID 23675315, 2013). "The aim of the present study is to investigate the role of BDNF functional Val66Met polymorphism (rs6265), three polymorphisms in NTRK2 gene (rs1387923, rs2769605 and rs1565445) and their interaction in pathophysiology of paranoid schizophrenia." (PMID 24069289, 2013). "A better knowledge of BDNF signaling in schizophrenic patients and controls may have important implications for the treatment of schizophrenia, considering current trends toward individualized medicine based in molecular biomarkers at gene and protein levels." (PMID 23785335, 2013).
schizophrenia (continued). "Evaluating co-morbidity free, antipsychotic-naïve schizophrenia patients for BDNF levels and examining the correlates of this factor with symptoms might facilitate elucidation of its pathogenetic role without confounds of potential influencing factors." (PMID 23847552, 2013). "The idea of a role for the D1R–D2R heteromer in contributing to disorders characterized by abnormal dopamine signaling is supported by studies showing an integral involvement of CaMKII, BDNF or GAD67 in the pathological processes underlying drug addiction and schizophrenia." (PMID 22428025, 2012). "By employing a multi analyte profiling proteomics approach in plasma samples from schizophrenic patients, Domenici and colleagues have found that BDNF may be a candidate biological marker for schizophrenia." (PMID 22654714, 2011). "Moreover, EGR3 is a downstream gene of many signaling pathways including pathways triggered by NGF, BDNF and NRG1, of which BDNF and NRG1 are schizophrenia susceptibility genes." (PMID 20156358, 2010). "Though functional alterations in BDNF, which plays important role in neuroplasticity, are implicated in many abnormalities found in schizophrenia, the regulatory mechanism(s) involved in the abnormal signaling of BDNF in schizophrenia is not clear." (PMID 18335055, 2008). "Moreover, postmortem studies using brain samples from different cohorts showed changes in BDNF expression as well as the expression of its receptor, TrkB, in different brain areas of subjects with schizophrenia." (PMID 18335055, 2008). "Similarly, mean BDNF mRNA levels were significantly reduced in schizophrenia group (34%; p = 0.0027) and bipolar group (40%; p = 0.003) as compared to the control group." (PMID 18335055, 2008). "Regarding psychiatric disorders, a correlation between BDNF low serum levels and schizophrenia was also demonstrated, up to the point that, albeit nonspecific, this abnormality has been considered a cue of involvement of neurotrophic processes in schizophrenia." (PMID 40141736, 2025). "Further evidence for disrupted BDNF-mediated trophic signalling in the midbrain are reductions in TrkBTK+ mRNA in both inflammatory schizophrenia subgroups compared to controls, demonstrating that reduced TrkBTK+ mRNA may be detected in the absence of overt tissue inflammation in schizophrenia." (PMID 40335479, 2025). "Moreover, there is ongoing research into potential biomarkers that could be additionally used to assess cognitive function in schizophrenia, such as brain-derived neurotrophic factor (BDNF), macrophage migration inhibitory factor and homocysteine." (PMID 40405881, 2025). "Different studies support the notion that impairments in the GABAergic system driven directly or indirectly by BDNF may play an important role in the pathophysiology of neurodevelopmental disorders like autism spectrum disorder, Rett syndrome, and schizophrenia, as mentioned." (PMID 39125882, 2024). "Recent studies also suggest that horticultural activities may improve BDNF levels in schizophrenia, enhancing self-regulation skills and providing opportunities for mindfulness among participants, thereby further contributing to the alleviation of depressive symptoms." (PMID 39517317, 2024). "This outcome may imply that a decrease in BDNF levels may not be the underlying cause of schizophrenia development in cannabis users." (PMID 38376038, 2024). "Furthermore, research has suggested that stress, one of the environmental factors associated with the development and exacerbation of schizophrenia, can have a negative impact on BDNF levels." (PMID 38673018, 2024). "In addition, abnormalities in the BDNF gene may influence the onset of affective psychiatric disorders and schizophrenia." (PMID 38397229, 2024). "By promoting BDNF expression and enhancing GluA1 phosphorylation, LT‐102 may contribute to the restoration of synaptic plasticity and cognitive function in individuals with schizophrenia." (PMID 38615362, 2024).